ZEB2 (zinc finger E-box binding homeobox 2)
Diseases named in the same sentence as ZEB2 in open-access papers (continued):
Sharing a sentence is not in itself a finding about the gene and the disease.
cancer (continued). "The results of recent studies suggest that members of the miR-200 family play a critical role in suppressing EMT and cancer invasion and metastasis by targeting transcriptional repressors of ZEB1 and ZEB2." (PMID 24598126, 2014). "The miR-200 family regulates negatively EMT and cancer cell migration in many different epithelial tumors by targeting ZEB1 and ZEB2, which act as transcriptional repressors of E-cadherin." (PMID 25058589, 2014). "Of particular importance are ZEB1 and ZEB2, which are crucial regulators of EMT during cancer development." (PMID 25269476, 2014). "The Wnt/β-catenin signal pathway promotes EMT in cancer, and miR-200a was found to inhibit Wnt/β-catenin by targeting ZEB1 and ZEB2." (PMID 24598126, 2014). "For example, in one study, overexpression of Stat3, PDGF-D, Notch-1, and DCLK1 in cancer cells led to significant downregulation of miR-200 family members; this resulted in up-regulation of ZEB1, ZEB2, and SNAI2 expression and acquisition of the EMT phenotype." (PMID 24598126, 2014). "Previous studies have demonstrated the function of many other transcription factors, such as ZEB2, E47, in controlling EMT during cancer progression." (PMID 23431386, 2013). "Following the knockdown of DCLK1, a significant downregulation of ZEB1, ZEB2, SNAIL and SLUG was observed following increased expression of pri-miR-200a in AsPC-1 cancer cells." (PMID 24040120, 2013). "Several target genes of miR-200a have been identified by comparing normal and cancer epithelial cells, such as ZEB1, ZEB2, SIRT1, and KEAP1." (PMID 23750238, 2013). "Recent studies have also identified the miR-200 family as a powerful marker and determining factor of the epithelial phenotype of cancer cells by targeting the E-CADHERIN repressors ZEB1 and ZEB2." (PMID 22876288, 2012). "ZEB2 has been suggested to mediate EMT and disease aggressiveness in several types of human cancers." (PMID 22393452, 2012). "Hence, ZEB2 may be an excellent anti-cancer therapeutic target." (PMID 21303533, 2011). "Thus, ZEB2 may be an important anti-cancer therapeutic target." (PMID 21303533, 2011). "For instance, up-regulation of SNAIL1, ZEB1, ZEB2 or E12 in epithelial cells represses E-cadherin expression and induces EMT in several carcinomas." (PMID 21464926, 2011). "The role of these miRNAs in cancer progression is based in part on their capacity to target the EMT activators ZEB1 and ZEB2, two transcription factors, which in turn repress expression of E-cadherin." (PMID 20682048, 2010). "Conversely, there are several reports that miR-200 family members and miR-192 can be down-regulated by TGF-beta, and this promotes EMT in cancer and other cell lines via subsequent up-regulation of targets ZEB1 and ZEB2 to repress E-cadherin." (PMID 21049046, 2010). "Of particular importance are ZEB1 and ZEB2 because they are crucial regulators of EMT during embryonic development and cancer." (PMID 20025777, 2009). "In ESCC, miR-200b suppresses cell growth and induces cell cycle arrest by modulating expression of cell cycle regulator genes and the Wnt/β catenin signaling pathway, and the miR-200 family post-transcriptionally suppresses ZEB1 and ZEB2, which are crucial EMT activators in various types of cancers." (PMID 40529228, 2025). "By binding to the promoter of the CDH1 (E‐cadherin) gene, SNAIL1, SNAIL2, and ZEB2 suppress CDH1 expression and increase CDH2 (N‐cadherin) levels, reducing cell adhesion and promoting mesenchymal traits such as increased motility and invasion in cancer cells." (PMID 41244070, 2025). "Moreover, TNF-α enhances the invasive characteristics of cancer cells through the induction of EMT, which is mediated by mechanisms dependent on Snail or ZEB1/ZEB2." (PMID 39941858, 2025).
cancer (continued). "Further analysis of differences in the expression of ZEB1, ZEB2, and CREB3L1, which are included in the GeoMx Cancer Transcriptome Atlas Panel gene list, revealed significant enrichment in Vim+ carcinoma cells relative to that in Vim− carcinoma cells from the nine ROIs." (PMID 39256881, 2024). "Therefore, it is necessary to develop anti‐cancer drugs that inhibit both ZEB1 and ZEB2 simultaneously, because ZEB1/2 are both deeply involved in the malignant differentiation of cancer cells." (PMID 39362647, 2024). "ZEB1 is one of the most extensively studied molecules in the field of EMT and cancer cell differentiation, while ZEB2 has not been researched in depth." (PMID 39362647, 2024). "High mRNA levels of RKIP correlated negatively with those of SNAIL1, SNAIL2, TWIST1, TWIST2, ZEB1, and ZEB2 in several but not all carcinomas." (PMID 39335152, 2024). "Moreover, a heatmap depicting ZEB1, ZEB2, CREB3L1, and CDH1 across the nine ROIs revealed clear segregation between Vim+ and Vim− carcinoma cells." (PMID 39256881, 2024). "In cancer cells, ERK5 either promotes or inhibits SNAIL function, although ERK5 activation usually promotes EMT by increasing the function of SLUG, ZEB1, and ZEB2." (PMID 37009481, 2023). "Moreover, this transcriptome reprogramming was accompanied by significant increase in ZEB1, ZEB2 and TWIST2 EMT-TFs in cancer cells." (PMID 36936987, 2023). "In cancer cell studies, SP1 was considered a key mediator of CYP1B1 action, whilst CYP1B1 was shown to activate a epithelial to mesenchymal transition and Wnt/beta-catenin-signaling pathways, upregulating beta-catenin and other TFs, such as ZEB2 and SNAI1." (PMID 37511270, 2023). "ZEB homeobox is a transcription factor family that includes ZEB1 and ZEB2, which may induce the EMT during cancer development." (PMID 37416766, 2023). "Next, RNA-Seq was conducted to explore the downstream gene of lnc-ZEB2-19, and RSPH14, a gene recognized as a prognostic marker in HCC20 and NSCLC34 for the promotion of cancer progression, was selected and demonstrated to be a common target of lnc-ZEB2-19 and TRA2A." (PMID 37564197, 2023). "ZEB2 has been identified as one of the key controllers of the epithelial-mesenchymal transition (EMT) process, which is important in the development and spread of cancer." (PMID 37927751, 2023). "In addition, β-catenin translocates into the nucleus and activates the expression of ZEB1, whereas Wnt signaling and E2F1 upregulate ZEB2 expression, resulting in EMT activation and cancer progression." (PMID 37444447, 2023). "Moreover, ZEB2 correlates with the infiltration levels of CD4+T cells in 20 cancer types, CD8+T cells in 24 cancer types, B cells in 18 cancer types, neutrophils in 29 cancer types, macrophages in 26 cancer types, and dendritic cells in 28 cancer types." (PMID 35723302, 2022). "Our previous study showed ZEB2 to be downregulated in cancers with nodal metastases compared with those without." (PMID 36140249, 2022). "Similarly, no significant expression changes were observed in the studied mesenchymal markers in the resistant cancer cells such CDH2, VIM, ZEB1, ZEB2, SLUG, TWIST1 that which are upregulated in completed EMT." (PMID 35523936, 2022). "Moreover, ZEB2 correlates with SMAD1 in 28 cancer types, SMAD2 in 27 cancer types, SMAD3 in 22 cancer types, SMAD5 in 28 cancer types, CTBP1 in 14 cancer types, and CTBP2 in 22 cancer types." (PMID 35723302, 2022). "All these data along with our results suggest the existence of coregulation between players in triplets such as OIP5-AS1–miR-203a–ZEB2 and OIP5-AS1–miR-203a–c-MET, which is imbalanced by cancer development and may stimulate EMT and metastasis of OC." (PMID 35453574, 2022). "Interestingly, ZFAS1 was negatively correlated with ZEB2, while NORAD was positively correlated with ZEB2 in PRAD cancer type." (PMID 36514044, 2022).
cancer (continued). "In the cancer context, increased activity of the LSD1/NuRD complex through oncogenes such us ZEB2 could lead to the same process of gene repression by poising gene expression and blocking differentiation at an immature and cancer stem cell-like state." (PMID 36229595, 2022). "As miR-200 family determines the epithelial phenotype of cancer cells by targeting the E-cadherin repressors ZEB1 and ZEB2 proteins, our results displays that HOTAIR induces the migration and metastasis of GC cells through miR-200 family, thereby affecting EMT." (PMID 34923813, 2022). "Both ZEB1 and ZEB2 induce EMT and enhance cancer progression." (PMID 35723302, 2022). "In malignant tumors, transcription factors like ZEB1 and ZEB2, SNAI1 and SNAI2, and Twist-related protein (TWIST) 1 and 2 may lead to migratory and invasive cancer cells." (PMID 35463825, 2022). "Previous reports identified the PI3K-Akt pathway as an enhancer of the expression of epithelial and mesenchymal transition (EMT) resultant transcription factors such as Snail, Slug, ZEB1, and ZEB2 that promoted the EMT and resulted in an elevation of the cancer cell motility." (PMID 36009568, 2022). "Furthermore, through the TCGA database we found that the mRNA expression levels of ZEB2 and TWIST1 were positively correlated across cancer malignancy stages (G1–G4) in 600 CRC patients." (PMID 35884488, 2022). "The EMT in cancer is a process of dedifferentiation due to external stimulation like TGF-β or IL-8, activation of transcription factors including Snail, Slug Twist, Zeb1, and Zeb2, or oncogenic signals like WNT, Notch, and MAPK pathways." (PMID 34622157, 2021). "Expression of TWIST1 and ZEB2 was largely absent in cancer cells, and, in 6 of the 8 cancer types, even the 95th percentile of Vimentin expression levels in cancer cells was lower than its average expression level in CAFs." (PMID 33972543, 2021). "In this review, we will focus on neurodevelopmental disorders and on important new lessons from other systems; we discuss ZEB2 neither in EMT/cancer nor in immune cells." (PMID 34356053, 2021). "This review attempts to summarize in detail, albeit without discussing ZEB2’s role in cancer, hematopoiesis, and its emerging roles in the immune system, how intense ZEB2 research has arrived at this exciting intersection." (PMID 34356053, 2021). "ZEB2 protein is important in EMT, a process that occurs in advanced stages of cancer development." (PMID 33803107, 2021). "The related pathways of ZEB2 are TGF-beta Receptor Signaling and MicroRNAs in cancer." (PMID 33499918, 2021). "MiR-139-5p was confirmed to negatively regulate ZEB1 and ZEB2 expression 31, which induces EMT and promotes the progression of malignant carcinoma 54, while overexpression of ZEB1 and ZEB2 abolishes the inhibitory effects of miR-139-5p on HCC cell migration and invasion." (PMID 34522182, 2021). "Zinc finger E-box-binding homeobox 1 (ZEB-1) and Zinc finger E-box-binding homeobox 2 (ZEB-2) are well-known drivers of epithelial-mesenchymal transition (EMT), which not only promote normal embryonic development but also contribute to cancer progression and metastasis." (PMID 32600257, 2020). "Indeed, H19 sponges miR-200a or miR-200b/c to promote cancer metastasis through ZEB1 and ZEB2 upregulations." (PMID 32610610, 2020). "The protein Zeb2 is a transcriptional repressor of E-cadherin and regulator of epithelial-to-mesenchymal transition (EMT), a process vital during physiological development and cancer progression." (PMID 33142861, 2020). "Unfortunately, there are currently no reports about the relationship between miRs and ZEB2 in cancer immunotherapy, and further studies can focus on revealing relationship between miR/ZEB2 axis and cancer immunotherapy." (PMID 32664703, 2020). "In conclusion, we identified in this study a panel of differentially expressed miRNAs and detected an upregulation of one the downstream targets, ZEB2, in carcinoma tissues of IBC vs. non-IBC." (PMID 32708601, 2020).
cancer (continued). "A significant inverse correlation between miR-203a-3p and ZEB2 was detected only in carcinoma tissues of non-IBC (r = −0.8, p < 0.05)." (PMID 32708601, 2020). "We also observed a decrease in cancer invasion and migration from TQ treatment as well as a reduction in the expression of EMT-related genes, such as N-cadherin, TWIST, SLUG, SNAIL, ZEB1 and ZEB2, including downstream MUC4." (PMID 31141941, 2019). "ZEB2 is reported to be a repressor of E-cadherin and the cadherin switching, like decrease in E-cadherin and increase in N-cadherin is a feature of EMT in malignant tumors." (PMID 30250401, 2018). "While expression of ZEB1 and ZEB2 is suppressed by epithelial miR‐200 family of miRNA, TGF‐β induces their expression in addition to some other EMT‐related transcription factors, including Snail, and Slug, in certain types of normal and cancer cells." (PMID 28618162, 2017). "Moreover, as an oncogenic lncRNA in multiple cancers, H19 functioned as miRNA sponge to lead to the de-repression of ZEB1 and ZEB2 genes in the mesenchymal cells." (PMID 29340065, 2017). "SNAI1, SNAI2, ZEB2, and VEGFA have been reported as miR-203 targets related to cancer invasion." (PMID 26882562, 2016). "Loss of expression of the miR-200 family members may play a critical role in the repression of E-cadherin by ZEB1 and ZEB2 during EMT, thereby enhancing migration and invasion during cancer progression." (PMID 27285757, 2016). "In cancer cells, EMT is a complex process, which may be regulated by multiple transcription factors such as Slug, Zeb1 and Zeb2." (PMID 26207647, 2015). "The high-grade budding cancer showed a nuclear translocation of β-catenin toward the invasion front, loss of membranous E-cadherin, absence of CDX2, and increased ZEB1 and ZEB2 in stromal cells at the invasion front." (PMID 25528769, 2015). "In out study, knockdown of ZEB2NAT reversed CAF-CM induced ZEB2 protein level and partially inhibits the CAF-CM induced cancer cell invasion, indicating that ZEB2NAT is one of the essential TGFβ1 downstream components involved in EMT and cancer cell invasion." (PMID 26152796, 2015). "ZEB2 is an important transcriptional factor in EMT and functions as a metastasis regulator via direct binding to the promoter site of the cell adhesion molecule E-cadherin in several cancer types." (PMID 24885194, 2014). "Both the NF-κB/IL6/JAK2/STAT3 cascade, which we show here is modulated by miR-221/222-mediated downregulation of ADIPOR1, and ZEB2 expression, which we have previously shown is repressed by TRPS1, are well-characterized effector pathways in cancer metastasis, invasion, and EMT." (PMID 23776679, 2013). "ZEB2 has been found to mediate the EMT and disease aggressiveness in various human cancers." (PMID 23658743, 2013). "Cancers with scores above the obtained cutoff value were considered to have high ZEB2 expression, which led to the greatest number of cancers classified, based on the presence or absence of a clinical outcome." (PMID 23658743, 2013). "In addition, downregulation of ZEB2 in HCC cell lines and cancers was found to be mediated by aberrant promoter methylation." (PMID 22393452, 2012). "ZEB2 has been suggested to mediate EMT and disease aggressiveness in various human cancers." (PMID 22393452, 2012). "Recently, several other groups have reported a role for the miR-200 family in the Epithelial-Mesenchymal-transition (EMT) and in cancer cell migration, the latter by directly targeting the transcription factors ZEB1 and ZEB2, which regulate E-Cadherin, a mediator of cell-cell adhesion." (PMID 20420713, 2010). "In cancers or fibrosis, this feedback loop may be disrupted, leading to unregulated expression of ZEB1 or ZEB2." (PMID 20025777, 2009). "The S1 subunit represses ZEB2, which may be positive from an anti-cancer point of view but negative with regard to wound healing in pulmonary epithelial tissue." (PMID 38674024, 2024).
cancer (continued). "Interestingly, the knockdown of cancer cell-derived immunoglobulin G (cancer-IgG) in SACC suppressed EMT by upregulating E-cadherin and downregulating ZEB1/ZEB2, suggesting that cancer-IgG could be a useful prognostic marker for this disease." (PMID 37296849, 2023). "Our results show that ZEB2 expression was lower in OV and many cancers compared to normal tissue." (PMID 35723302, 2022). "In our study, we showed that PA2G4 enhanced the migration and invasion ability of cancer cells, induced a rearrangement of F-actin and modulated the expression of EMT-related molecular markers (E-cadherin, N-cadherin, occluding, Vimentin, α-SMA and ZO-1) as well as TFs (ZEB1, ZEB2 and Snail)." (PMID 35526051, 2022). "Hence, the ZEB2/TWIST1 co-repression of E-cadherin appears to be ubiquitous and crucial, providing potential targets for clinical diagnosis and therapeutical design for malignant carcinomas." (PMID 35884488, 2022). "In addition, ZEB1, ZEB2, PTEN, and SEPT7 were regulated by the three candidate miRNAs, and many studies confirm the prominent role of these genes in several biological processes and cancer progression." (PMID 34692473, 2021). "Besides, ZEB1 has been reported to help cancer cells develop resistance to radiation via stabilizing CHK1, while ZEB2 could protect cancer cells from UV or cisplatin induced apoptosis." (PMID 28416756, 2017). "We found that ZEB2 did not always have the same prognostic significance and clinicopathological association as ZEB1, especially when performing subgroup analyses according to cancer type." (PMID 28416756, 2017). "ZEB1, ZEB2, SNAI1, and TWIST1 drive EMT of cancer cells, but they are not required for metastasis in animal models." (PMID 34339740, 2021). "ZEB1 and ZEB2 are known to be extensively upregulated by TGF-β in both normal epithelial cells and cancer cells." (PMID 31682640, 2019). "Correspondingly, certain lung cell lines from the Cancer Cell Line Encyclopedia (CCLE) that highly express TM4SF5 exhibited a positive correlation with ESRP1/2 expression and negative correlation with ZEB2 expression." (PMID 31501417, 2019). "The low-grade budding cancer, having no buds to analyze, showed the membranous β-catenin, intact E-cadherin, nuclear CDX2 and absence of ZEB2." (PMID 25528769, 2015). "Moreover, recently published ZEB2 chip-Seq data, using human cancer cell lines, indicated that CDH1 (the E-cadherin gene) was not a target of ZEB2, it was not enriched by ChIP and furthermore, E-cadherin expression was not increased by depletion of ZEB2." (PMID 29963231, 2018).